KPNA2P3 (karyopherin subunit alpha 2 pseudogene 3)
Gene: Transcribed unprocessed pseudogene on chromosome 17 (64,749,918 to 64,758,603, reverse strand). Ensembl gene ENSG00000266820.
Diseases named in the same sentence as KPNA2P3 in open-access papers:
KPNA2P3 is named in the same sentence as 1 disease in open-access papers, as found by Europe PMC text mining. Sharing a sentence is not in itself a finding about the gene and the disease.
KPNA2P3 shares sentences with these, for which no sentence is quoted: tumor (1 paper).